TREM2 (triggering receptor expressed on myeloid cells 2)
Diseases named in the same sentence as TREM2 in open-access papers (continued):
Sharing a sentence is not in itself a finding about the gene and the disease.
tumor (continued). "Previous studies have suggested that TREM2+ TAMs could promote tumor progression in renal tumors and impede the antitumor immune response in a mouse tumor model." (PMID 37187751, 2023). "Interestingly, we noted that Trem2+ cells from our mouse BCC tumor model clustered most closely with Trem2+ cells from other tumor models and not from normal or wounded tissues." (PMID 37164949, 2023). "Deficiency or absence of TREM2 enhances the effects of therapeutic drugs and restrains overall tumor growth." (PMID 37335084, 2023). "To further verify whether the tumor will recur after PD-1 scFv, TREM2 scFv, and BsAb treatment, we extended the cycle of oncology treatment to 35 days." (PMID 37563723, 2023). "Additionally, we found a proliferative TREM2+VCAM1+ macrophage primarily residing in the LT region (which we termed SCAMs) that possesses the surprising capacity to directly regulate LY6D- tumor epithelial proliferation via the secretion of OSM ligand." (PMID 37164949, 2023). "Indeed, by predicting L:R interactions between GBM tumor cells and monocyte‐derived macrophages, we revealed that there was more putative TREM2 signaling in co‐cultures that exhibited strong macrophage polarization." (PMID 37791581, 2023). "Similarly, TREM2, an established marker for post-surgical recurrence of ccRCC30, shows higher expression in a large proportion of the pro-tumour TAM and tissue-resident monocytes for patient HG_3 with recurrent ccRCC." (PMID 37696903, 2023). "Altogether, these findings indicated that TREM2 might play a crucial role in the changes in the tumor immune microenvironment and the progression of SKCM." (PMID 36741909, 2023). "Blocking TREM2+ macrophages limit tumour growth and augment anti-PD1 therapy." (PMID 37965573, 2023). "The top hit from the BrafV600E;Cas9 screen included Trem2, a known regulator of immune response with unknown function in tumor cells 55,64,65." (PMID 37258521, 2023). "In addition, it will provide information on the immunosuppressive environment created by tumor infiltrating immune cells expressing TREM2." (PMID 36119485, 2022). "Along with TREM2, these cells were enriched for genes involved in lipid metabolism (APOE), immunosuppression (MARCO, CD163, CD81), and the complement cascade (C1QB), suggesting that TREM2 specifically marks a subset of tumor-specific immunosuppressive macrophages." (PMID 35746551, 2022). "However, we discovered that TREM2 is uniquely expressed in tumor-derived DCs and macrophage subsets." (PMID 35967424, 2022). "This highlights the importance of patient stratification to score TREM2/TAM enrichment and identify tumor types that may be more responsive to TREM2-targeting therapies." (PMID 35746551, 2022). "In addition, it was suggested that genetic excision of TREM2 significantly inhibited the accumulation of myeloid cells within the tumor, leading to immune reactivation." (PMID 36438899, 2022). "The hepatic environment might therefore represent a unique site where TREM2 impact on tumor growth is influenced by tissue-specific factors and cell types, and this still needs to be further investigated." (PMID 35746551, 2022). "However, we found a similar percentage of TREM2+ TAMs in the flow cytometric analyses of tumor tissue and healthy adjacent tissue." (PMID 36230558, 2022). "A comparison of tumors to healthy tissues showed an accumulation of TREM2+ macrophages in all the analyzed tumors (lung, colon, liver, breast, stomach, and pancreas datasets), and TREM2+ TAMs were also enriched at the patient level in tumor tissues (liver, lung, and colon datasets)." (PMID 35746551, 2022). "The interplay between stromal cells in the TME is complex, and while it is unlikely that TREM2 impacts the tumor via a single mechanism, these data indicate that key mechanisms are through suppression of cytotoxic T lymphocytes and recruitment of regulatory T cells." (PMID 36119485, 2022).
tumor (continued). "Additionally, the data suggest that the presence of TREM2+ cells in the tumor stroma contributes to the suppression of these cytotoxic T lymphocytes and their ability to control tumor growth." (PMID 36119485, 2022). "In other cancers, TREM2+ macrophages were found within both the tumor nest and tumor stroma." (PMID 36119485, 2022). "Furthermore, Trem2-deletion increased the infiltration of NK cells and cytotoxic T cells in the tumor, whereas PD-1- and Tim-3-expressing T cells were reduced." (PMID 35746551, 2022). "TREM2 may have tumor cell intrinsic functions in addition to its role in stromal cells and fibroblasts that could be tumor suppressive or oncogenic depending on the type of cancer." (PMID 36119485, 2022). "Additionally, the injection of TREM2+ DCs into these cancer-bearing mice led to accelerated tumor progression and worsened survival." (PMID 36031601, 2022). "In vitro and in vivo studies suggest that TREM2 may contribute to tumor suppressing activity in CRC and HCC." (PMID 36119485, 2022). "Subcutaneous injection of cells with TREM2 knockdown resulted in increased tumor volume suggesting TREM2 may also contribute to tumor suppressing activity in HCC." (PMID 36119485, 2022). "Therefore, to determine which types of immune cells were tightly correlated with TREM2 in the tumor microenvironment, we performed a CIBERSORT analysis in three databases." (PMID 36713360, 2022). "Considering the correlation between high TREM2 expression and poor prognosis, we hypothesized that TREM2 may enhance tumor immune evasion." (PMID 36713360, 2022). "Finally, the level of TREM2 presence within TAMs has been positively correlated with tumor staging, including the degree of nodal metastases." (PMID 36031601, 2022). "It has been suggested that anti-inflammatory TREM2 signaling may interfere with intrinsic mechanisms to combat neoplasia and promote profibrotic responses following liver damage." (PMID 35359989, 2022). "The emerging body of literature on the subject of TREM2 expression by the epithelial tumor cells is seemingly contradictory, with some studies suggesting TREM2 contributes to tumor suppressive activity and other studies suggesting it supports oncogenic activity." (PMID 36119485, 2022). "The absence of TREM2 caused significant changes in the tumor immune landscape, in both the myeloid and the lymphoid compartments." (PMID 35746551, 2022). "We will also highlight the impact of TREM2 targeting in tumor models and its clinical applications." (PMID 35746551, 2022). "Similarly, modulation of TAM function via TREM2 inhibition or small-molecule inhibitors of PI3Kγ also relies on combinations with CPI to demonstrate tumor growth regression in preclinical models." (PMID 35179953, 2022). "Targeting TREM2 remodels the tumor myeloid landscape to reduce the tumor growth." (PMID 36510315, 2022). "It is, thus, suggested that the antitumor effect of si-TREM2 may be related to the alteration of the tumor microenvironment." (PMID 36438899, 2022). "This review will focus on the role of TREM2 in cancer, including patient survival data and TREM2 expression in human tumor samples, as well as a discussion of the potentially oncogenic or tumor suppressive roles of TREM2 when expressed by the epithelial tumor cells." (PMID 36119485, 2022). "Therefore, moving forward it is imperative that we better understand the mechanisms by which TREM2 contributes to tumor suppressive or oncogenic activity in the cancer types discussed in this review." (PMID 36119485, 2022). "We noticed that TREM2 was expressed almost exclusively in tumor-derived cells." (PMID 35359989, 2022). "Gene intersection and survival analysis showed that there were 435 DEG crosses in PTC patients and genome-wide tumor samples, only CXCL10, CD40LG, KRT14, TRAT1, and TREM2 were associated with patient prognosis, and TCGA showed that only the TREM2 expression was upregulated in PTC." (PMID 36438899, 2022).
tumor (continued). "TREM2 might serve as a therapeutic target to modify tumor myeloid infiltrates and augment checkpoint immunotherapy." (PMID 35795050, 2022). "Considering the substantial link between TREM2 and macrophages, we hypothesized that TREM2 might be expressed in tumor-infiltrated macrophages." (PMID 36713360, 2022). "Single-cell RNA sequencing of cells isolated from the tumor scaffolds highlighted two macrophage subpopulations characterized by increased gene expression of either C1qa, C1qb and Trem2 (Cq macrophages) or Chil3, Ly6c2 and Plac8 (Chil macrophages), respectively." (PMID 35740692, 2022). "Within a recent study, the authors examined TREM2 function in TAMs of distinct tumor models." (PMID 34539650, 2021). "Since detection of TREM-2 ex vivo is limited, the tumor microenvironment may have prevented us from detecting TREM-2, possibly through masking or cleavage of the receptor." (PMID 35223446, 2021). "Having identified Chil3, Trem2, and the complement genes, C1qa and C1qb as markers of SAMs in tumor-bearing mice, we next investigated whether these macrophage subsets also exist in primary tumors." (PMID 33782087, 2021). "Therefore, we examined the expression of ligands for TREM-1 and TREM-2 on tumor-infiltrating myeloid cells using TREM/Fc chimeras." (PMID 35223446, 2021). "This study can provide insight into the role of TREM2 in tumor immunotherapy." (PMID 33679809, 2021). "Additionally, on day 25, the tumor volume in TREM2-TG mice treated with TREM2-Ig (TG + TREM2-Ig) was higher (1988.14 ± 426.2 mm3) than that in TREM2-TG mice treated with hu-Ig (TG + hu-Ig) (970.3 ± 257.11 mm3)." (PMID 33980160, 2021). "Moreover, diverse correlations were detected between TREM2 expression levels and different subsets of tumor infiltrating T cells." (PMID 33679809, 2021). "We hypothesized that TREM-1 would be overexpressed on MDSC in tumor-bearing mice and that TREM-2 would be co-expressed on MDSC and TAM in tumor-bearing animals." (PMID 35223446, 2021). "Furthermore, recent scRNA-seq studies of the tumor microenvironment (TME) have revealed that TREM2 is expressed in several subgroups of myeloid cells, some of which overlap with MDSCs according to various definitions." (PMID 33679809, 2021). "In conclusion, a growing body of evidence suggests that TREM2 acts as a key signaling hub in tumorigenesis, tumor progression and oncotherapy, and TREM2 may play different or even opposite roles in different malignancies." (PMID 34539652, 2021). "Taken together, our data suggest that manipulation of the TREM-1/TREM-2 balance in tumors may be a novel means to modulate tumor-infiltrating myeloid cell phenotype and function." (PMID 35223446, 2021). "Similar to the SAMs, the TAMs in the primary tumor separated into two populations: one with high expression of Chil3, Plac8, and Ly6c2 (Chil-TAMs), and the other with high expression of C1qa, C1qb, and Trem2 (Cq-TAMs)." (PMID 33782087, 2021). "Then, we used an in vivo tumor model to determine whether TREM2 signaling affects the antitumor effect of BM-derived immune cells." (PMID 33980160, 2021). "In addition, we established a tumor-bearing mouse model to demonstrate that the NK cell population increased via TREM2 overexpression, which reduced tumor progression." (PMID 33980160, 2021). "Trem2 gene knockout model mice are more resistant to the growth of various cancers, and checkpoint immunotherapy can be improved by the TREM2 function of modifying tumor myeloid infiltrates." (PMID 33679809, 2021). "Thus, TAM and Mo-MDSC are the most likely sources of Trem2 within the tumor, whereas PMN-MDSC and TAM are the primary sources of Trem1." (PMID 35223446, 2021). "We hypothesized that TREM-1 and TREM-2 might be co-expressed on tumor-infiltrating myeloid cells and that elevated sTREM-1 associates with disease outcomes, thus representing a possibility for mutual modulation in cancer." (PMID 35223446, 2021).
tumor (continued). "In contrast, TREM2 levels were downregulated in tumor relative to normal tissues in LUSC and LUAD." (PMID 33679809, 2021). "Moreover, CD45.2+ NK1.1+ cells persisted in tumor-bearing mice transplanted with a TREM-2-TG-BM at day 41 post adaptive transplantation." (PMID 33980160, 2021). "Furthermore, tumor-infiltrating macrophages can express TREM2, leading to an immunosuppressive microenvironment, which can, in turn, promote tumor growth, but inhibit the anti-tumor immune response." (PMID 33955820, 2021). "Furthermore, 27 days post-inoculation, the survival rate (75%) of tumor-bearing mice transplanted with a TREM2-TG-BM was significantly higher than that of WT-BM-transplanted mice (0%)." (PMID 33980160, 2021). "Trem2 knockout mice exhibited decreased recruitment of myeloid regulatory cells in tumours that was associated with increased T and NK cell functionality and reduced tumour growth, thus highlighting the potential therapeutic effect of targeting Trem2 signalling to reduce immune suppression activity." (PMID 34685679, 2021). "Furthermore, anti-TREM2 mAb dampened tumor growth and highly enhanced the efficiency of anti-PD-1 immunotherapy." (PMID 33381508, 2020). "Conversely, we found a higher percentage of CD14+ TREM-2+ monocytes in better surviving patients; these cells could downregulate the exaggerated inflammation and potentiate the phagocytosis in the tumor." (PMID 32684831, 2020). "In these studies, tumor-bearing mammary fat pads underwent ASC population shifts from ASC2 to ASC1 in tumor-bearing mice as well as changes in macrophage expression patterns linked to inflammatory responses, such as increased Trem2 and Irf8." (PMID 33088423, 2020). "We found a higher percentage of CD14+ TREM-2+ monocytes in better surviving patients; these cells could downregulate the exaggerated inflammation and potentiate the phagocytosis in the tumor." (PMID 32684831, 2020). "Indeed, authors showed that Trem2–/– mice were more resistant to tumor growth than WT mice in a mammary tumor mouse model." (PMID 33381508, 2020). "A further mechanistic study based on a PCR array revealed that TREM2 may exert a tumor inhibitory role in HCC through the PI3K/Akt signal pathway." (PMID 30683932, 2019). "In conclusion, our study identified TREM2 as a tumor suppressor in HCC." (PMID 30683932, 2019). "The number of tumor foci found in the lungs in the mice injected with TREM2 knockdown MHCC97L cells was markedly higher than that in the control mice, which could be rescued by β-catenin interference." (PMID 30683932, 2019). "Further rescue assays in vitro and in vivo indicated that the tumor-promoting effect of TREM2 knockdown could be rescued by β-catenin interference." (PMID 30683932, 2019). "In the present study, we report that TREM2 is a novel tumor suppressor in HCC." (PMID 30683932, 2019). "Herein, we investigated TREM2 expression in tumor and matched non-tumor tissues of HCC patients." (PMID 30683932, 2019). "Second, we have sequenced the coding and untranslated regions of TREM2 gene in matched non-tumor and tumor tissues, and found no mutations." (PMID 30683932, 2019). "In order to determine whether the tumor mediated the induction of TREM-2 in vitro, we prepared CM for DC and MΦ derivation." (PMID 27102437, 2016). "More TREM-2+DCs were detected in the lung of 3LL tumor-bearing mice." (PMID 27102437, 2016). "Here we focused on DCs to investigate the effect of TREM-2 during tumor immunoregulation." (PMID 27102437, 2016). "Furthermore, TREM-2+DCs from tumor-bearing mice and CM produced less IL-12 but more IL-10, In addition, we also collected DCs from CM on day 5 and tested its OVA uptake to investigate their endocytosis phenomenon." (PMID 27102437, 2016). "We speculated that tumor microenvironment may promote monocytes to differentiate into MΦs and induce TREM-2 expression." (PMID 27102437, 2016). "TREM-2+DCs from the lung of tumor-bearing mice present an MHC IIlow CD80low CD86lowphenotype." (PMID 27102437, 2016).
tumor (continued). "Concurrently, we also observed that the percentage of TREM-2+CD11c+DCs markedly increased in the lung tissue of orthotopic 3LL tumor model, and more TREM-2+DCs and TREM-2+MΦs could be derived from CM added with the 3LL supernatant." (PMID 27102437, 2016). "Such TREM-2+DCs not only presented impaired phenotypes and reduced OVA-endocytic capacity but also exercised a more potent inhibitory effect on the proliferation of T cells, suggesting that TREM-2 may exert a negative regulation in tumor immunity." (PMID 27102437, 2016). "Here, we observed that more TREM-2+ DCs and TREM-2+MΦs were induced by the tumor microenvironment." (PMID 27102437, 2016). "Additionally, within the tumor microenvironment, two distinct tumor-associated macrophage (TAM) clusters were enriched in PitNETs, one with pro-inflammatory M1 features and the other with immunosuppressive M2 marker upregulation (SPP1, TREM2, and CX3CR1)." (PMID 40959438, 2025). "Mechanistic and translational studies further support TREM2 as a therapeutically tractable macrophage checkpoint; effector-enhanced anti-TREM2 antibodies and modalities delivering TREM2-directed binders into the tumor bed improve responses to PD-1 therapy, including in CRC models." (PMID 41567197, 2025). "However, in high-grade serous cancer (HGSC) with high infiltration of immune cells, TREM2 may play a key role in regulating the polarization of TAMs towards the M1 phenotype, thereby contributing to the promotion of anti-tumor immune responses." (PMID 40242752, 2025). "However, in oncology, the anti-inflammatory and immunosuppressive effects of TREM2 may facilitate tumor growth and immune evasion." (PMID 40242752, 2025). "Notably, TREM2 has been identified as a novel anticancer target, with high expression in tumor-associated macrophages (TAMs) and minimal or no expression in macrophages within normal peripheral tissues." (PMID 40242752, 2025). "Importantly, genetic knockdown of TREM2 or pharmacologic blockade of its downstream kinases significantly mitigates MNT formation, reduces the integration of these cells into tumor-associated neural networks, and correlates with alleviation of chronic cancer-associated pain in preclinical models." (PMID 41009819, 2025). "Similarly, in triple‐negative breast cancer, this axis drives the recruitment of monocytes to tumor sites, where they differentiate into a specific subpopulation of lipid‐associated macrophages characterized by STAB1 and TREM2 expression, which exhibit immunosuppressive properties." (PMID 40692664, 2025). "We next validated whether CCL8 mediated the pro-tumor effect of TREM2+ TAMs." (PMID 41253786, 2025). "For example, in certain types of tumors, TREM2 may promote tumor immune escape." (PMID 40028337, 2025). "Notably, in certain cancers, TREM2 exhibits duality depending on the type and stage of the cancer and may either promote or inhibit tumor growth." (PMID 40242752, 2025). "Moreover, differential gene expression analysis revealed that the expression of Gzmb was significantly greater in proliferating CD8+ T cells and memory CD8+ T cells in tumor samples derived from the Trem2−/− BMDM group than in those derived from the WT BMDM group." (PMID 39838454, 2025). "Thus, targeting TREM2+ TAMs might reshape the tumor immune microenvironment and enhance the immunotherapy efficacy." (PMID 41253786, 2025). "However, the phagocytic effects of TREM2 on tumor cells and the ligands that bind to TREM2 to exert specific phagocytic functions remain unclear." (PMID 39135069, 2024). "Therefore, enhancing the potential of myeloid cells in TME to phagocytose tumor cells by inducing TREM2-mediated phagocytosis could be a potential immunotherapeutic strategy for the treatment of brain tumors." (PMID 38725629, 2024).